STAT3 (signal transducer and activator of transcription 3)
Diseases named in the same sentence as STAT3 in open-access papers (continued):
Sharing a sentence is not in itself a finding about the gene and the disease.
tumor (continued). "After isolating only the malignant tumor cells, we analyzed IL‐6/STAT3 signaling and the resistant and sensitive signatures of TMZ extracted from analyzing Depmap data in four clusters." (PMID 41556041, 2026). "The protective effect of STAT3 activation on tumor cell apoptosis following drug treatment is closely associated with the regulation of specific genes." (PMID 41539998, 2026). "Consistent with in vitro data, p‐STAT3+CK19+ tumor cells were most abundant in DKK3‐expressing CAF contexts." (PMID 41147409, 2026). "Beyond its canonical role in inflammatory and oncogenic signaling, STAT3 links tumor cell plasticity, immune suppression, and metabolic adaptation across the tumor ecosystem." (PMID 42238578, 2026). "A study addressing the chemotherapy-induced apoptosis of tumor cells confirmed that fatty acid β-oxidation triggers the acetylation of STAT3 by increasing acetyl-CoA." (PMID 41513612, 2026). "This was validated by immunohistochemistry, which showed that the relative expression levels of the p-JAK2 and p-STAT3 proteins were highest in the tumor tissues of the model group." (PMID 40351419, 2025). "In short, the mTOR and JAK pathways affects the activation of STAT3, which leads to tumour development and progression." (PMID 40407951, 2025). "STAT3 activation in the tumor microenvironment is regarded as an oncogenic event in addition to its typical cell functions." (PMID 40943427, 2025). "Some, such as ATG7, function as tumor suppressors, whereas oncogenic factors like Ras and signal transducer and activator of transcription 3 are frequently overexpressed in breast cancer and contribute to tumor progression." (PMID 40384989, 2025). "Flavonols also block the continuous activation of transcription factors like NF-κB and STAT3 that promote tumor progression." (PMID 40808836, 2025). "In contrast, tumor volumes in mice treated only with STAT3 ASOs were 277.4 ±53.8 and 1042.9 ±326.8 mm3, respectively." (PMID 40166646, 2025). "Our results open new avenues for developing antitumor agents with atypical mechanisms of action targeting tumor cell metabolic pathways through STAT3-mediated modulation of glycolytic function." (PMID 41226114, 2025). "STAT3 is aberrantly activated in both tumor cells and astrocytes, where it drives the production and secretion of pro-tumorigenic signaling molecules, contributing to the formation of an immunosuppressive metastatic microenvironment." (PMID 40733107, 2025). "Piperlongumine, a natural alkaloid, suppresses osteosarcoma cell growth, migration, invasion, and EMT by downregulating the SOCS3/JAK2/STAT3 pathway via inhibition of miR-30d-5p, thereby reducing tumor aggressiveness in OS cells." (PMID 40941019, 2025). "Growing evidence indicates that inhibiting STAT3 activity in cancer cells can suppress tumor growth and increase chemotherapy sensitivity in HCC cells." (PMID 40740310, 2025). "In the TME, the IL-6/JAK/STAT3 signaling can drive the proliferation, survival, invasion, and metastasis of tumor cells and strongly suppress the anti-tumor immune response." (PMID 40568576, 2025). "The interplay between STAT3 and autophagy can have either synergistic or antagonistic roles at different stages of tumor development." (PMID 40601671, 2025). "CUR and RES have emerged as potential therapeutic agents due to their ability to inhibit the STAT3 pathway, reducing tumor growth, angiogenesis, migration, and invasion." (PMID 40860906, 2025). "Signal transducer and activator of transcription 3 (STAT3) is a key mediator of inflammation and tumor progression." (PMID 39981236, 2025). "Functional investigation has shown that TSM-1 promotes cell cycle arrest and apoptosis in tumor cells by reducing the expression of critical downstream STAT3 effectors." (PMID 40426875, 2025).
tumor (continued). "Oncostatin M (OSM), an IL-6 family cytokine primarily secreted by immune cells, has been shown to activate the STAT3 pathway in tumor cells via the OSM receptor (OSMR), thereby promoting tumor proliferation and metastasis." (PMID 41383622, 2025). "STAT3 functions as a transcription factor that, when persistently activated, promotes an inflammatory tumor microenvironment, enhances stemness-related gene expression, and supports immune suppression." (PMID 40722714, 2025). "In line with our findings, STAT3 localises to focal adhesions in cancer cells and, upon activation, contributes to tumour metastasis through increased expression of cell adhesion molecules." (PMID 40309782, 2025). "In LY2 and MOC2 tumor‐bearing mice, the average tumor volumes following combined radiation and STAT3 ASO treatment were 53.0 ±5.6 and 254.8 ±81.6 mm3, respectively." (PMID 40166646, 2025). "In parallel, SH003 remodels tumor immunity by attenuating STAT3-driven PD-L1 signaling, promoting macrophage repolarization, and enhancing cytotoxic lymphocyte activity." (PMID 41228309, 2025). "This study investigates a novel approach using exosomes in combination with lipid nanoparticles to deliver RNA molecules that silence the STAT3 gene, which plays a key role in tumor growth." (PMID 40427146, 2025). "HSV expressing PTEN (HSV-P10, oHSV-P10) has been shown to regulate the PI3K/AKT and IL6/JAK/STAT3 signaling pathways, reduce PD-L1 expression in tumor cells, and decrease tumor immune escape." (PMID 40872965, 2025). "Tumor-derived CXCL8 fosters M2 TAM polarization by activating the STAT3 signaling pathway and concurrently hurdles PD-1+ CD8+ T cell recruitment." (PMID 40607254, 2025). "Unlike immune checkpoint markers such as PD-L1, which primarily modulate T-cell activity, STAT3 drives oncogenic processes directly by promoting tumor cell survival, proliferation, and metastasis." (PMID 40636126, 2025). "The complex downregulatedVEGF and exerted antiproliferative activities in tumor tissue throughinhibiting STAT3-directed transcription and repressed angiogenesisin a mouse xenograft model." (PMID 41152016, 2025). "In vivo studies show that RES can suppress tumor growth by 40%–50% by inhibiting the STAT3/HIF‐1α/VEGF axis." (PMID 40860906, 2025). "We propose that the utility of the STRESS signature is such that it predicts how a tumor will dynamically respond to STAT3 signaling resulting from inflammation and oxidative stress and identifies tumors likely to respond to STAT3-targeted therapies." (PMID 40701148, 2025). "Among the key regulators, STAT3 signaling emerged as a central mediator of this reprogramming and was effectively inhibited by small-molecule intervention, reversing aspects of the tumor-educated phenotype." (PMID 41514627, 2025). "In a preclinical cerebellopontine schwannoma mouse model, treatment with an angiotensin‐receptor blocker (losartan) as an anti‐fibrotic through inhibition of IL‐6/STAT3 and TGF‐β, reduced the amount of collagen I and prevented tumor‐induced hearing loss." (PMID 39506612, 2025). "The hyperactivated IL6/JAK/STAT3 can facilitate tumor cell proliferation and invasiveness; hence treatments targeting the IL6/JAK/STAT3 pathway are expected to inhibit tumor cell growth." (PMID 41044672, 2025). "The aberrant activation of JAK2/STAT3 signaling has been detected across multiple solid tumors, where it drives tumorigenesis, tumor survival, proliferation, and metastatic." (PMID 40309242, 2025). "Ligation of TLR7 in the K-ras mouse model vigorously accelerated tumor progression, interfaced with canonical NF-κB/MAPK cascades, induced STAT3 activation and caused loss of p16 and PTEN." (PMID 41465346, 2025). "The role of Jak2/Stat3 signaling in NB has been widely investigated, with evidence demonstrating that this pathway promotes tumor cell growth and apoptosis resistance." (PMID 40429864, 2025).
tumor (continued). "The introduction of STAT3-specific short hairpin RNA into diethylnitrosamine-induced HCC mouse models can inhibit tumor progression as well, indicating the carcinogenic role of STAT3 in HCC." (PMID 40822972, 2025). "IL-6 secreted by CAFs activates the Janus Kinases/Signal Transducer and Activator of Transcription 3 (JAK/STAT3) signaling pathway in tumor cells, thereby enhancing stemness, EMT, and resistance to apoptosis." (PMID 40940809, 2025). "While we see tumor-intrinsic effects of STAT3 inhibition in terms of reduced tumor cell proliferation, we do not see changes in angiogenesis or apoptosis markers (data not show)." (PMID 40356899, 2025). "The use of antisense oligonucleotides, such as CpG-STAT3ASO or AZD9150, has been shown to effectively silence STAT3 in myeloid cells, enhancing anti-tumor immune responses." (PMID 40050933, 2025). "The binding of EUDAL to EGFR prevents its ubiquitination and degradation, facilitates its sustained phosphorylation, and subsequently activates downstream STAT3 signaling, which leads to autophagy-related drug resistance in tumor cells." (PMID 40940319, 2025). "In vivo validation confirmed that pharmacological CCR7 or STAT3 inhibition markedly reversed chemoresistance and potentiated cisplatin-induced tumor cell death." (PMID 40898244, 2025). "Based on the research above, precision targeting of the spermine-STAT3-APOE axis represents a promising strategy to remodel the tumor microenvironment and enhance the efficacy of ICB therapy in AEG." (PMID 40963562, 2025). "Targeting PARN in GSCs reduces tumor infiltration and prolongs survival in orthotopic brain tumor xenografts, suggesting that the STAT3-PARN regulatory network plays a pivotal role in tumor progression and represents a potential target for GBM therapeutics." (PMID 40277888, 2025). "In short, we developed a novel metal-Cp*-based STAT3 inhibitor with anti-proliferative and anti-migratory capabilities, which is expected to be further used in tumor chemotherapy and immunotherapy." (PMID 39697768, 2025). "Tumor-derived exosomes mediated immune suppression of monocytes via altered STAT3, increased expression of arginase, and levels of reactive oxygen specie (ROS)." (PMID 40443670, 2025). "Lactate regulates MDSC activation through the GPR81/mTOR/HIF-1α/STAT3 pathway, and blocking lactate production in tumor cells restores anti-tumor T cell responses." (PMID 40650086, 2025). "It promotes the phosphorylation of STAT3, thereby enhancing the proliferation and survival of tumor cells." (PMID 40647128, 2025). "This multifaceted role of STAT3 encompasses the regulation of protein and lipid metabolism, appetite control, and tumor immune responses." (PMID 40704145, 2025). "IL6 is frequently upregulated in GBM, where it activates JAK/STAT3 signaling to promote tumor cell survival, proliferation, and therapy resistance, and contributes to an immunosuppressive milieu." (PMID 41031155, 2025). "More importantly, phosphorylation of the transcription factor signal transducer and activator of transcription 3 (p-STAT3) is a biomarker of tumor growth and metastasis, which was decreased after RFA treatment after MELK deprivation and RFA treatment." (PMID 39871325, 2025). "MEF2C is predominantly expressed in the tumor core of both LSCC and LUAD, underscoring its association with cancer cell proliferation and its potential regulatory interaction with STAT3." (PMID 41373817, 2025). "Exosomes encapsulated with curcumin, along with a STAT3 inhibitor, resulted in a significant reduction in tumor volume in the mouse tumor model." (PMID 40761875, 2025). "Icaritin inhibits the IL‐6/JAK2/STAT3 pathway by blocking the phosphorylation of JAK2 and STAT3, which suppresses downstream gene expression, prevents STAT3 nuclear translocation, and reduces tumor cell proliferation." (PMID 40035422, 2025).
tumor (continued). "Immunohistochemical results were consistent with in vitro, and elevated RP11-54O7.17 significantly reduced the protein content of S100A4, p-STAT3 and Ki-67 in tumor tissues and suppressed the expression of p-STAT3 and S100A4." (PMID 41173847, 2025). "This chimera achieved efficient STAT3 gene silencing in vitro and significantly suppressed tumor growth and angiogenesis in vivo in a GBM xenograft model." (PMID 41245487, 2025). "Of those studied here, STAT3 and MYC are important in both type I and type III latency, and depletion or inhibition of these proteins causes EBV to reactivate and/or the tumor cells to die." (PMID 40354417, 2025). "For example, macrophages in SCLC secrete interleukin-6 (IL-6), which activates the signal transducer and activator of transcription 3 (STAT3) signaling pathway to promote tumor growth." (PMID 41194225, 2025). "The altered expression of NOVA1 promotes tumor progression in CRC patients by modulating JAK2/STAT3 pathway." (PMID 39980011, 2025). "The suppression of the STAT3 downstream genes suppressed tumor growth and metastasis and significantly prolonged the survival of the mice." (PMID 41331510, 2025). "Next, we evaluated the effect of impaired neutrophil-STAT3 signaling on tumor growth and progression." (PMID 40885734, 2025). "In a metastatic RCC there is evidence that IL-6 levels are greatly increased as part of the tumour milieu to promote evasion of the adaptive immune response by arresting dendritic cell processing and leading to increased intracellular STAT3 signaling." (PMID 40610926, 2025). "This study investigates the role of Prkci in regulating tumor angiogenesis through the Jak2/Stat3 signaling pathway." (PMID 40840329, 2025). "After administering NLP-EXOSOME COMPLEX/STAT3-silencer treatment, we observed a significant increase in survival rate and decrease in tumor size." (PMID 40427146, 2025). "For example, Tumor-Associated Macrophages (TAMs) can secrete IL-6, which induces EMT in primary tumor cells through JAK2/STAT3 signaling, yielding anoikis-resistant CTCs." (PMID 41239272, 2025). "It shows strong antiproliferative effects in STAT3-driven leukemia and lymphoma models and leads to complete tumor regression in xenograft mice." (PMID 40507351, 2025). "Given the strong link between STAT3 activation and EMT in OS, inhibiting STAT3 signaling represents a viable approach for limiting tumor progression, metastasis, and drug resistance." (PMID 40941019, 2025). "Compared to the model group, the mRNA expression levels of JAK2 and STAT3 in the tumor tissues of the Nolvadex group were significantly lower (P < 0.01)." (PMID 40351419, 2025). "In contrast, STAT3 phosphorylated at Ser727 localises to mitochondria, which modulate the activity of the electron transport chain, ultimately suppressing tumour cell apoptosis." (PMID 41463025, 2025). "These pro-inflammatory cytokines not only sustain chronic inflammation but also contribute to tumor initiation and progression by activating oncogenic signaling pathways, including NF-κB and STAT3, which in turn stabilize β-catenin signaling." (PMID 41199821, 2025). "PM2.5 induces LOC146880 expression, invasion, and migration in lung cancer cells, while arsenic induces Lnc‐DC expression and promotes tumour formation through STAT3/ PD‐L1 in arsenic‐transformed cells." (PMID 40783798, 2025). "Mechanistically, HMP1G NPs downregulated tumor cell‐derived IDO1 via the aryl hydrocarbon receptor/signal transducer and activator of transcription 3/interleukin signaling axis to improve kynurenine/tryptophan metabolism and immunosuppression." (PMID 39661740, 2025). "Jadwiga Jablonska’s pioneering work on neutrophil-specific STAT3 targeting revealed the therapeutic potential of reprogramming neutrophils from tumor-promoting to tumor-suppressing phenotypes." (PMID 41141601, 2025). "The differentiation of TAMs in tumor site was controlled by the downregulation of STAT3 transcription activity." (PMID 40380196, 2025).
tumor (continued). "The STAT3 signaling system has been developed as a favorable goal for anti-tumor therapy due to its several effect pathways in tumor growth, metastasis, microenvironment development, and immunosuppression." (PMID 40217305, 2025). "Recent studies have identified key pathways involved in tumor-derived exosome-mediated macrophage transformation, including the NF-κB and STAT3 signaling pathways, as well as hypoxic conditions." (PMID 40028322, 2025). "While TXNIP and IL-24 act as tumor suppressors, STAT3 is considered an oncogene, being constitutively activated in nearly 70% of solid and hematological tumors." (PMID 40175348, 2025). "The phosphorylation of STAT3 initiates the transcription of many genes, including genes responsible for oncogenesis and tumour progression." (PMID 40729003, 2025). "It has been demonstrated that tumor-infiltrated MDSCs (compared to normal splenic myeloid cells) express higher levels of lipid transport proteins, induced by tumor-derived cytokines (G-CSF and GM-CSF) and through STAT3 and STAT5 signaling." (PMID 40696413, 2025). "Once in the lung microenvironment, these microbes modulate epithelial signaling, enhance immune evasion, and activate tumor-promoting pathways such as NF-κB, signal transducer and activator of transcription 3 (STAT3), and β-catenin." (PMID 41463196, 2025). "By inhibiting JAK1/2 and suppressing IL-6/STAT3 signaling, Momelotinib reduced tumor growth and metastasis." (PMID 41463071, 2025). "Therapeutic targeting of STAT3 must therefore be carefully balanced to avoid inadvertently promoting tumor progression while alleviating cachexia." (PMID 40704145, 2025). "In contrast, tumor-suppressor miRNAs, such as miR-124, miR-139-5p, miR-193a-3p, miR-122, miR-192, and miR-495 counteract inflammatory processes by inhibiting NF-κB, STAT3, and Wnt signaling, thereby reducing tumor cell proliferation and enhancing apoptosis." (PMID 40943532, 2025). "The FXR agonist obeticholic acid (OCA) induces cell cycle arrest and suppresses tumor cell invasion via STAT3 dephosphorylation and SOCS3 upregulation, concomitant with reduced IL-6/STAT3 signaling and pro-inflammatory cytokine (IL-1β, IL-6) secretion." (PMID 40980688, 2025). "Persistent or dysregulated STAT3 activation has been shown to drive tumor cell proliferation, apoptosis evasion, and immune modulation, thereby promoting resistance to CDK4/6 inhibitors." (PMID 40303916, 2025). "STAT3-driven upregulation of c-Myc enhances the expression of metabolic and biosynthetic genes required for tumor growth, while the activation of anti-apoptotic genes such as Bcl-2 ensures cellular survival during rapid proliferation." (PMID 40278288, 2025). "The STAT3/HIF‐1α/VEGF signaling pathway plays significant roles in promoting tumor growth and progression, such as regulating cellular responses to low oxygen levels (hypoxia) and promoting the expression of genes that support tumor growth and angiogenesis." (PMID 40860906, 2025). "The JAK/STAT3 pathway not only affects the tumor immune microenvironment but is also related to tumor progression directly." (PMID 40179015, 2025). "Reactive astrocytes with STAT3 create a favorable environment around the metastatic lesion, facilitating tumor progression." (PMID 39858080, 2025). "Mechanistically, TLR4‐initiated signaling converges with STAT3 phosphorylation, facilitating its nuclear translocation, where STAT3 dimerizes with cofactors to transactivate tumor angiogenesis‐related genes." (PMID 40727252, 2025). "PDLIM2, a PDZ-LIM domain-containing protein expressed highest in the lung and immune cells, serves as a unique tumor suppressor and immune modulator, mainly by turning off the activation of the master transcription factors NF-κB and STAT3." (PMID 41000764, 2025). "Blockade of IL-6 in mice has been shown to significantly inhibit lung cancer progression, tumor cell–intrinsic STAT3 activation, tumor cell proliferation, and angiogenesis." (PMID 40746594, 2025).